ATRX (ATRX chromatin remodeler)
Diseases named in the same sentence as ATRX in open-access papers (continued):
Sharing a sentence is not in itself a finding about the gene and the disease.
glioma (continued). "Moreover, ATRX is involved with the telomerase-independent alternative lengthening of telomeres (ALT) mechanism, and the ATRX gene is also involved in the regulation of the tumor microenvironment in glioma." (PMID 38385046, 2024). "Additionally, in a study focusing on grade 2 gliomas, none of the IDH-mutated, 1p/19q co-deleted tumors showed ATRX loss." (PMID 39165459, 2024). "Secondly, the molecular detection information was not complete and did not include 1p/19q co-deletion, ATRX mutation, EGFR amplification, etc., but this molecular information was of great significance to the diagnosis and treatment of glioma, so it needs to be improved in future research." (PMID 36614997, 2022). "However, unlike the HeLa ATRX KO clones, the ATRX KO glioma cell lines used in this study showed similar levels of γH2AX as compared to the EV cells." (PMID 35406561, 2022). "Interestingly, the preoperative McCormick grade significantly affected the overall survival, and molecular markers such as Ki-67 and ATRX show an effect on prognosis which has not been described in intramedullary gliomas before." (PMID 33094355, 2021). "Second, despite the IDH1R132H mutation being the most influential genetic factor for postoperative oncological outcomes of gliomas, information concerning other potential factors such as the chromosomal 1p/19q codeletion, IDH2 or MGMT mutation, and ATRX mutation was not considered." (PMID 34389754, 2021). "In addition, low ATRX expression was positively correlated with tumor type (recurrent) (P < 0.0046), 1p/19q non-codeletion (P < 0.0001), IDH status (mutant) (P < 0.0001), and subgroups of glioma with LGG and GBM." (PMID 33194637, 2020). "Therefore, through our modulation of ATRX expression in glioma cell lines, we have confirmed that most cell lines do not develop ALT characteristics after ATRX loss." (PMID 30226859, 2018). "Therefore, it appears that additional mechanisms of tumorigenesis are involved in higher-grade gliomas and the role of ATRX is not specific in this category of tumors." (PMID 29034211, 2017). "However, gliomas typically do not express histiocytic markers and exhibit other molecular characteristics, including IDH mutations, ATRX alterations, 1p/19q co-deletions, EGFR amplification, TERT promoter mutations, H3 mutations, MYB/MYBL1 gene structural mutations, and FGFR1 mutations, etc." (PMID 40231251, 2025). "For example, five-year survival of patients with gliomas containing IDH mutation or ATRX mutation (IDH and ATRX are mutually exclusive) and 1p/19q co-deletion is up to 80%, whereas those with gliomas not containing IDH or ATRX mutation and without 1p/19q codeletion is 5%." (PMID 35884406, 2022).
glioma (continued). "We show through the direct measurement of telomerase activity and ALT in a large set of glioma samples that the TMM in glioma cannot be defined solely by the combination of telomerase activity and ALT, regardless of TERT expression, TERT promoter mutation, and ATRX loss." (PMID 35953846, 2022). "In contrast, while 5/6 NF1-associated gliomas epigenetically aligning with IDH-wildtype glioblastoma harbored either CDKN2A homozygous deletion or CDK4 amplification similar to NF1-associated HGAP, only one of these six tumors had ATRX mutation, and none exhibited piloid features." (PMID 35945463, 2022). "Moreover, DAXX mutations are not generally found in adult low-grade gliomas, indicating that DAXX-independent mechanisms of mutant ATRX may play a role in the phenotype of these tumour cells." (PMID 35382567, 2022). "The histopathological diagnosis was a glioma, not otherwise specified (NOS) without WHO grading which was IDH1 (R132H) antibody-negative, 1p/19q non-codeleted, and ATRX retained." (PMID 31806041, 2019). "As opposed to the “all gliomas” group, EGFR was overexpressed in all tumors (100%) of IDH-mutant 1p/19q co-deleted ATRX-wt WHO grade-II regardless of the rs55705857 genotype." (PMID 27282637, 2016). "Likewise, in the scATAC-seq of murine IDH-mutant gliomas, we also observed significant enrichment for CTCF and CTCFL motifs in the peaks that were specific to ATRX-wildtype tumors, but we found no enrichment in ATRX-KO peaks." (PMID 34763709, 2021). "Moreover, BCAT1 is an independent prognostic factor for glioma patients, high BCAT1 expression is related to unfavorable clinical parameters including older age, IDH wildtype, no 1p/19q codeletion, ATRX wildtype and MGMT unmethylated." (PMID 33493139, 2021).
glioma (continued). "As expected, we found highly frequent ATRX inactivation (∼92.9%) in TERT wild-type gliomas in the present study, and demonstrated that the RTL was significantly longer in ATRX-negative tumors than that in ATRX-positive tumors (Median, 0.90 vs. 0.49; P = 0.002)." (PMID 26556853, 2016).
astrocytomas (186 papers, 2012 to 2026). "ALT is particularly prevalent in certain subtypes of malignant gliomas, such as IDH-mutant astrocytoma and pediatric glioblastoma, and frequently co-occurs with ATRX (ATRX chromatin remodeler) inactivating mutations." (PMID 41520142, 2026). "Astrocytomas with the ATRX mutation were found in seven of the 15 drug resistance epilepsy samples but were absent in drug-responsive epilepsy." (PMID 40103938, 2025). "Compared to oligodendrogliomas and GBM, astrocytomas showed a significantly lower proportion of ATRX+ tumor cells, which is also consistent with the phenotype of ATRX mutations in astrocytomas." (PMID 40264576, 2025). "TERT mutations present in the vast majority of oligodendroglioma and IDH wildtype glioblastoma are mutually exclusive with ATRX mutations and alternative lengthening of telomerase seen in astrocytoma." (PMID 40949165, 2025). "Strikingly, 92% of oligodendrogliomas harbored active TERTp mutations, compared to 12.2% in astrocytomas, thus highlighting mutual exclusivity between ATRX and TERTp alterations." (PMID 41377022, 2025). "Regarding diagnosis, 96% (51/53) of astrocytomas were classified as ALT + (42 of which showed ATRX loss), along with 73% (14/19) of histone-mutant tumors, consistent with previous studies." (PMID 41422096, 2025). "The majority of the ATRX-mut astrocytomas exhibited enrichment of gene ontology (GO) terms associated with immune-related pathways, including activation of innate immune response, PRR activation, and response to IFNα and β." (PMID 38272925, 2024). "The ATRX mutation is found in around 75% of grade 4 astrocytomas and rarely in IDH wild-type glioblastomas (only 3%)." (PMID 38633919, 2024). "Given the fact that the mutation of ATRX and the codeletion of 1p/19q are mutually exclusive, it has been stated that ATRX mutation is more specific to astrocytoma IDH-mutant CNS WHO grade 4." (PMID 39057054, 2024). "For this, labels were prepared based on tumor-specific markers (e.g., ATRX-loss in high-grade IDH1 astrocytoma as represented in Var1)." (PMID 38263411, 2024). "ALT activation is described in sarcoma, astrocytoma, neuroblastoma, and carcinoma cases as well as CM and is related to functional loss of ATRX and/or histone H3.3 chaperone DAXX." (PMID 37629169, 2023). "The diagnosis of astrocytoma requires either the immunohistochemical loss of nuclear ATRX expression or detection of a pathogenic ATRX mutation or the exclusion of combined whole-arm deletions of 1p and 19q." (PMID 36717507, 2023).
astrocytomas (continued). "Out of the 22 IDH-mutated infiltrating astrocytoma cases with interpretable ATRX IHC, 12 showed evidence for loss of ATRX expression in neoplastic cells." (PMID 36397144, 2022). "The astrocytomas commonly have loss of α-thalassemia mental retardation X-linked (ATRX), which is retained in oligodendrogliomas, and astrocytomas frequently have TERT promoter mutations." (PMID 36428772, 2022). "The case suggests that loss or inactivation of ATRX can be associated with malignant transformation of astrocytoma." (PMID 36147920, 2022). "Somatic ATRX gene mutations are associated with several different tumor types, including astrocytomas in adults and neuroendocrine tumors (NETs) such as pancreatic NETs, neuroblastomas, and paragangliomas/pheochromocytomas." (PMID 33106857, 2021). "ATRX mutations have been observed in 71% of grade II-III astrocytoma, 68% of oligoastrocytoma, and 57% of secondary GBM." (PMID 34912706, 2021). "On the other hand, ATRX mutations are mutually exclusive from 1p19q co-deletion, but are associated with IDH1 mutation, suggesting that ATRX drives the lineage-specific formation of astrocytomas." (PMID 32120790, 2020). "Astrocytomas have an additional mutation for the ATRX gene whereas oligodendrogliomas show a 1p19q co-deletion." (PMID 32218467, 2020). "Astrocytomas are typically characterized by loss-of-function mutations in ATRX, which are tightly associated with the alternative lengthening of telomeres (ALT) phenotype." (PMID 32904945, 2020).
astrocytomas (continued). "Demonstration of the ATRX mutation or loss of ATRX nuclear expression is recommended for the diagnosis of astrocytoma." (PMID 29058264, 2018). "The incidence of ATRX mutation is higher in diffuse lower grade astrocytomas, compared with oligodendrogliomas and GBMs." (PMID 29359122, 2017). "Frequently, mutations of ATRX are found in 67% of grade 2 astrocytomas, 73% of grade 3 astrocytomas, and in 57% of secondary GBMs, but rarely in primary GBM (4%)." (PMID 27338365, 2016). "Recent reports described that ATRX mutation or loss occurred at high percentages in multiple tumor types, including low grade astrocytoma and secondary glioblastoma, suggestive of a potential “driver” role in cancer." (PMID 25971279, 2015). "In our study, we also showed that decreased ATRX mRNA expression was characteristically enriched in low-grade astrocytomas and this ATRX alteration significantly overlapped with IDH1/2 mutations (P<0.0001)." (PMID 24810474, 2014). "Another study using whole exome sequencing in four low grade astrocytomas, followed by focused resequencing in an additional 28 samples found a high incidence of mutations in the ATRX gene." (PMID 24202337, 2013). "ATRX was frequently mutated in grade II-III adult astrocytomas (71%), oligoastrocytomas (68%), and secondary glioblastomas (57%)." (PMID 24202337, 2013). "Taken together, these findings indicate that ATRX mutation itself represents the defining molecular abnormality of a distinct astrocytoma subclass delineated by gene expression." (PMID 23104868, 2012). "This is the first study to show that ATRX is associated with DRE in low-grade astrocytomas." (PMID 40103938, 2025). "Through their effects on the immune microenvironment and cytokine production, IDH and ATRX mutations in glioblastoma and astrocytoma promote immune suppression, and may be a potential therapeutic target for prolonging patient survival." (PMID 39479502, 2024). "It was predicted that all 28 of the IDH-mutant infiltrating astrocytomas would have loss of ATRX." (PMID 36397144, 2022). "However, loss of nuclear ATRX expression is easily detectable by immunohistochemistry to distinguish IDH-mutant astrocytomas from IDH-mutant and 1p/19q-codeleted oligodendrogliomas." (PMID 35361262, 2022). "In addition, infratentorial IDH-mutant astrocytomas have a loss of nuclear ATRX expression as well as MGMT promoter methylation in only ~50% of patients." (PMID 33293629, 2021).